PPIG (peptidylprolyl isomerase G)
Description:
PPIase that catalyzes the cis-trans isomerization of proline imidic peptide bonds in oligopeptides and may therefore assist protein folding. May be implicated in the folding, transport, and assembly of proteins. May play an important role in the regulation of pre-mRNA splicing.
Synonyms: CARS-Cyp; SRcyp; SCAF10; CYP
Tractability: Small molecule: a structure with a bound ligand is known. PROTAC: UniProt records ubiquitination sites on it; ubiquitination databases record sites on it; its protein half-life has been measured; a small molecule that binds it is known.
Target class: Isomerase; Enzyme
Gene: Protein-coding gene on chromosome 2 (169,584,342 to 169,641,408, forward strand). Ensembl gene ENSG00000138398.
Subcellular location: Nucleus matrix; Nucleus speckle
Subcellular location (Human Protein Atlas): Nuclear speckles; Cytosol
Pathways (Reactome):
Disease: SARS-CoV-1 activates/modulates innate immune responses
Metabolism of RNA: mRNA Splicing - Major Pathway
Gene Ontology:
Molecular function: peptidyl-prolyl cis-trans isomerase activity; protein binding; RNA binding; cyclosporin A binding
Biological process: protein folding; RNA splicing
Cellular component: nuclear matrix; nuclear speck; cytosol; nucleoplasm; nucleus; nuclear lumen
Genetic constraint (gnomAD): Loss-of-function variants: 24 observed, 71.57 expected, observed/expected ratio (o/e) 0.34, 90% interval 0.24 to 0.47. The upper end of that interval is the gene's LOEUF score, 0.47, which puts it in group 2 of 6, group 1 being the genes least tolerant of losing a copy. Missense variants: 692 observed, 819.07 expected, observed/expected ratio (o/e) 0.84, 90% interval 0.79 to 0.9. Synonymous variants: 283 observed, 260.2 expected, observed/expected ratio (o/e) 1.09, 90% interval 0.99 to 1.2.
Homologues: Orthologues: chimpanzee PPIG (99% identical), macaque PPIG (99% identical), dog PPIG (95% identical), guinea pig PPIG (95% identical), rabbit PPIG (95% identical), pig PPIG (95% identical), rat Ppig (93% identical), mouse Ppig (93% identical), tropical clawed frog ppig (60% identical), zebrafish ppig (51% identical), Drosophila melanogaster Moca-cyp (35% identical), Caenorhabditis elegans cyn-9 (17% identical), and 1 more. Paralogues in human: NKTR (39% identical), CWC27 (16% identical), PPID (15% identical), PPIL4 (14% identical), PPIB (12% identical), PPIC (12% identical), PPIA (11% identical), PPIE (11% identical), PPIH (11% identical), PPIF (11% identical), PPIL2 (11% identical), PPIL6 (10% identical), and 10 more.
Diseases named in the same sentence as PPIG in open-access papers:
PPIG is named in the same sentence as 61 diseases in open-access papers, as found by Europe PMC text mining. Sharing a sentence is not in itself a finding about the gene and the disease. The quoted sentences say what the papers report.
breast carcinoma (8 papers, 2019 to 2025). "Therefore, SLC2A1 and PPIG both appear to be significant prognostic markers in patients with HER2-positive breast cancer." (PMID 40004024, 2025).
colorectal cancer (1 paper, 2025). A primary or metastatic malignant neoplasm that affects the colon or rectum. "Additionally, mutations in the splicing factor PPIG led to widespread alternative splicing changes, which were validated through perturbation experiments in colorectal cancer cells." (PMID 40702779, 2025). "To further investigate the role of PPIG in modulating RNA splicing in colorectal cancer, we knocked down its expression in human colorectal carcinoma cell line HCT116 using small interfering RNA (siRNA) transfection and performed long-read RNA sequencing." (PMID 40702779, 2025).
cancer (18 papers, 2011 to 2025). A tumor composed of atypical neoplastic, often pleomorphic cells that invade other tissues. "PPIG is shown to play a crucial role in maintaining RNA splicing fidelity and regulating cancer-associated splicing programs." (PMID 40702779, 2025). "In contrast, splicing alterated genes in PPIG mutant cancer cells were associated with cell cycle regulation and cellular organization processes, potentially promoting more aggressive tumor behavior." (PMID 40702779, 2025). "We found that a splicing factor PPIG was mutated in patient CRC05, which has also been previously identified in multiple cancer types." (PMID 40702779, 2025). "Differential alternative splicing analysis was conducted for PPIG mutant and PPIG wild-type cancer cells, respectively, in comparison with normal epithelium." (PMID 40702779, 2025). "Notably, eight differential alternative splicing events significantly overlapped between PPIG knockdown vs. NC groups in HCT116 and PPIG mutant cancer cells vs. normal epithelial cells in CRC05 (hypergeometric test, P-value = 0.015)." (PMID 40702779, 2025).
tumor (13 papers, 2011 to 2025). "Moreover, mutated PPIG was linked to widespread splicing dysregulation, and functional validation experiments confirmed its critical role in modulating RNA splicing and tumor-associated processes." (PMID 40702779, 2025). "Additionally, we identified key proteins, including ANXA1, SLC2A1, and PPIG, which contribute to the tumour progression and resistance phenotype." (PMID 40004024, 2025).
PPIG also shares sentences with these, for which no sentence is quoted: infection (7 papers); viral infection (4); colitis (3); Anxiety (2); cardiovascular diseases (2); Cirrhosis (2); depression (2); diabetes (2); fungal infection (2); hepatocellular carcinoma (2); neurodegenerative disease (2); Obesity (2); porphyria (2); psychiatric diseases (2); Stroke (2); allergic disease (1); Alzheimer disease (1); asthma (1); autoimmune disease (1); brain tumor (1); cholestasis (1); colon cancer (1); congenital adrenal hyperplasia (1); fibrosis (1); Galactorrhea (1); gastric cancer (1); Gilbert syndrome (1); glioma (1); gynecologic tumors (1); Hepatitis (1).
A further 27 diseases each share a sentence with PPIG in 1 paper.